LAG3 (lymphocyte activating 3)
Diseases named in the same sentence as LAG3 in open-access papers (continued):
Sharing a sentence is not in itself a finding about the gene and the disease.
cancer (continued). "A comprehensive and systematic analysis of LAG3 would facilitate a comprehensive evaluation of LAG3 in cancer biology and provide valuable insights for cancer management." (PMID 38115039, 2023). "Co-inhibitory immune checkpoints, such as PD1, CD47, CTLA4 and LAG3, are highly expressed on T cell in a variety type of cancers, leading to attenuated T cell responses and ultimately immune evasion of cancer cells." (PMID 38035111, 2023). "Given the intricate expression pattern of LAG3 across different cancers, comprehensive exploration of this receptor from a pan-cancer perspective is imperative." (PMID 38115039, 2023). "Evidence showed that the low expression of LAG-3 was substantially linked to longer relapse-free and overall survival times, making relatlimab, which acts as a LAG3 inhibitor, a promising anti-cancer agent." (PMID 36765782, 2023). "Inhibition of LAG-3 is now being evaluated in clinical testing for the management of various cancers, such as breast carcinoma." (PMID 37469419, 2023). "The expression of LAG3 was found to be downregulated in several cancer types, including COAD, KICH, LIHC, PRAD, READ, THCA and UCEC." (PMID 38115039, 2023). "Pan-cancer analysis investigated the possible relationships between LAG3 expression and genetic alterations, RNA methylation modification-related genes, genomic instability, immune checkpoint genes, and infiltration of immune cells." (PMID 38041068, 2023). "Taken together, LAG-3-directed therapies constitute a new member of the therapeutic arsenal of cancer patients." (PMID 37509517, 2023). "Immunotherapies directed at immune checkpoints, including LAG-3, have become a promising strategy for controlling malignant tumors and chronic viral diseases." (PMID 36680187, 2023). "When FGL1 combines with LAG-3 on the surface of T cells, immune system mistake cancer cells as normal, contributing to immune-escape of tumor cells." (PMID 36911712, 2023). "Multiple established cancers that are resistant to PD-1 blockade alone are cleared as a result of the dual blockade of LAG-3 and PD-1." (PMID 36677919, 2023). "These recent developments highlight the promise of simultaneously targeting PD-1/PD-L1 and TIGIT or LAG-3 pathways for cancer immunotherapy." (PMID 37332070, 2023). "Given its important biological role, LAG-3 is considered a promising target for cancer immunotherapy." (PMID 37670328, 2023). "To date, more than twenty anti-LAG-3 antibodies have been used in clinical trials for cancer immunotherapy." (PMID 37670328, 2023). "Overexpression of LAG-3 enables cancer cells to escape immune surveillance, while its blockade reinvigorates exhausted T cells and strengthens anti-infection immunity." (PMID 37302810, 2023). "In preclinical studies, TIGIT and LAG-3 inhibitors are effective in combination with PD-1 inhibitors in various cancer models, such as melanoma, lung cancer, and ovarian cancer." (PMID 37031434, 2023). "Increased RAMP1 expression was strongly associated with the upregulation of lymphocyte activation gene 3 (LAG3), vascular endothelial growth factor B (VEGFB), and cytotoxic T-lymphocyte-associated protein 4 (CTLA-4) across multiple cancer types." (PMID 37796823, 2023). "We next examined the associations of TLR4 expression with 8 immune checkpoints (PD-L1, CTLA4, HAVCR2, LAG3, PDCD1, PDCD1LG2, SIGLEC15, and TIGIT), and TLR4 expression was widely associated with the 8 immune checkpoints in most cancer types." (PMID 37576399, 2023). "To summarise, dermatological effects secondary to LAG‐3 inhibitor use are apparent in patients with cancer." (PMID 38047262, 2023). "Collaboration between LAG-3 and PD-1 promotes cancer cell immune evasion and obstructing both LAG-3 and PD-1 is considerably more effective and less harmful for treating solid tumors that are advanced or have metastasized." (PMID 37841254, 2023). "LAG3 expression was correlated with prognosis in multiple cancers, particularly MPM; LAG3 is an independent prognostic biomarker of MPM." (PMID 38062416, 2023).
cancer (continued). "In this study we provide preclinical evidence that strongly supports the clinical development of multispecific checkpoint inhibitors targeting PD-L1, TIGIT, and LAG-3 as promising cancer immunotherapy agents." (PMID 37332070, 2023). "In conclusion, this is the first extensive research about the expression profiles, prognostic values, and functional significance of LAG3 in human pan-cancers." (PMID 38115039, 2023). "LAG3 includes domains that bind major histocompatibility complex class II with high affinity and contribute to escape from the cancer immune system." (PMID 38062416, 2023). "As TCGA cohort revealed that LAG3 mRNA is expressed at higher or lower levels in cancers than in normal tissues, we explored the prognostic potential of LAG3 mRNA expression in multiple cancers from TCGA database." (PMID 38062416, 2023). "T cell immunoreceptor with Ig and ITIM domains (TIGIT) and Lymphocyte-activation gene 3 (LAG3) are other immune checkpoints that have been targeted for cancer treatment." (PMID 37987252, 2023). "Taking the immune checkpoint gene LAG3 as an example, RNF31 expression was positively correlated with LAG3 in almost all cancers." (PMID 37117215, 2023). "Because LAG-3 ligation triggers a negative regulatory signal, this can result in immune tolerance and cancer immune escape." (PMID 37009054, 2023). "In this study, we revealed that LAG3 mRNA is expressed at higher or lower levels in cancers than in normal tissues and demonstrated that LAG3 was associated with prognosis in multiple cancers." (PMID 38062416, 2023). "Although there are studies evaluating LAG-3 in many types of cancer, very few studies have evaluated LAG-3 in TNBC." (PMID 36945923, 2023). "Given its substantial involvement in cancer immunity and tumorigenesis, LAG3 has garnered attention as a promising prognostic biomarker and a potential target for immunotherapy." (PMID 38041068, 2023). "Here, we performed a comprehensive analysis of LAG3 through multiple bioinformatics platforms to explore the functional roles of LAG3 in pan-cancer." (PMID 38115039, 2023). "A translational use of the synergistic approach between LAG-3 and PD-1 in cancer is highlighted by the positive clinical effects of LAG-3 blockage given the immune regulatory function of LAG-3." (PMID 36677919, 2023). "This suggests that cancer cells can evade immune response via upregulating PD-L1 and ligands for LAG-3 and TIM-3." (PMID 37446039, 2023). "Since immune checkpoint inhibitors (ICIs) have been a prominent topic in cancer treatment, the expression of eight ICIs (LAG3, HAVCR2, CD27, TNFRSF14, CTLA4, TMIGD2, TIGIT, and PDCD1LG2) were analyzed between groups in the study." (PMID 37405988, 2023). "In recent years, there has been a growing body of literature examining the relationship between LAG3 expression and survival outcomes in different types of cancer." (PMID 38041068, 2023). "Immunotherapy directed at immune checkpoints, such as LAG-3, has arisen as a promising strategy for controlling malignant tumors and chronic viral diseases." (PMID 36680187, 2023). "It is important to note that the field of Lag-3 and immunotherapy is still evolving, and more research is needed to fully understand its role and potential in cancer treatment." (PMID 37345057, 2023). "Its binding to LAG3 results in T cell depletion, mechanisms of immune evasion of the cancer and resistance to anti-PDCD1/CD274 therapy." (PMID 37215135, 2023). "The novel immunotherapy agents such as inhibitors of PDCD1, TIGHT, IDO1, CD274, CTLA4 and LAG3 were considered had potential survival benefit in several cancers." (PMID 37608927, 2023).
cancer (continued). "Accumulating evidence has indicated that LAG3 plays an important role in the immune system and survival in various cancers." (PMID 38062416, 2023). "Dysfunctional CD8+ T cells in cancer are characterized by high expression of inhibitory receptors, including PD-1, TIM-3, and LAG-3, which are positively associated with T cell exhaustion." (PMID 37122692, 2023). "The tSNE analysis showed that the LAG-3 expression was enriched in TILs compared to PBMCs from either healthy donors or cancer patients." (PMID 37795090, 2023). "In the context of immunotherapy, Lag-3 has gained attention as a potential target for cancer treatment." (PMID 37345057, 2023). "Future research is supposed to further investigate the possible synergy between LAG3 and other biomarkers in predicting cancer prognosis and treatment response." (PMID 38041068, 2023). "To test this possibility, we incubated cancer cells (RKO that express endogenous PD-L1) with Jurkat T cells that express LAG-3 or TIGIT, in the presence of GB265, GB266, GB266T, or control monospecific antibodies." (PMID 37332070, 2023). "The co-inhibitory receptor on LAG3 has been widely accepted as a potential target for cancer immunotherapy, and it is also expressed highly in the CLR-low group." (PMID 36983639, 2023). "Although lymphocyte activation gene-3 (LAG-3) directed therapies demonstrate promising clinical anti-cancer activity, only a subset of patients seems to benefit and predictive biomarkers are lacking." (PMID 36859619, 2023). "Blocking inhibitory receptors such as PD-1, CTLA-4 or Lag-3 have reversed this exhausted state in clinical trials of T cells in cancer." (PMID 36768336, 2023). "Across cancer types profiled in The Cancer Genome Atlas and confirmed by IHC in this study, LAG-3 expression in DLBCL was among the highest described, emphasizing a potential role for anti-LAG-3 immunotherapy." (PMID 37857711, 2023). "To take a step towards investigating the feasibility of ex vivo gene therapy, we used Cas9-HiFi RNP to introduce a nucleotide substitution in LAG3, a gene often modified to optimize chimeric antigen receptor-T cells for cancer treatment." (PMID 37474806, 2023). "We conducted comparative analyses of differential expression profiles and gene alterations of LAG3 between cancer and normal tissues, and evaluated their prognostic significance on the prognostic values and immune responses." (PMID 38115039, 2023). "Clinical trials of LAG3 monoclonal antibody (LAG3Ab) for various cancers are being proceeded in full swing." (PMID 35894707, 2022). "Opdualag will boost the entry of more LAG-3 targeting molecules into clinical practice, supporting the accumulating evidence highlighting the pivotal role of LAG-3 in cancer." (PMID 35954196, 2022). "Generally, the LAG-3 molecule detected on T cells is regarded as a marker of aggressive progression of cancers." (PMID 35494015, 2022). "LAG-3 inhibitors, together with CTLA-4 or PD-1/PD-L1 inhibitors, have been extensively explored in the different clinical trials for cancer therapy, which can not only avoid drug tolerance but also improve the clinical efficacy of LAG-3 inhibitors." (PMID 35958563, 2022). "Our results demonstrated the significantly negative correlations of m7Gscore with the expression of IDO1, PDCD1, and LAG3, which have been considered as important targets for cancer immunotherapy." (PMID 36246663, 2022). "LAG3 has been reported to play a negative regulatory role in cancer immunology by interacting with its ligands." (PMID 35873497, 2022). "For example, higher LAG-3 expression is correlated with longer survival in cancers such as advanced gastric cancer and esophageal adenocarcinoma." (PMID 36359346, 2022). "The clinical success of ICB has given it great relevance in the field of cancer IT and has led to the development of several new directions, including the investigation of other ICBs such as LAG-3, TIM-3, and NKG2." (PMID 35205776, 2022).
cancer (continued). "Apart from PD-1 and PD-L1 being targets of cancer immunotherapy, lymphocyte-activation gene 3 (LAG-3) is also identified as an immune checkpoint." (PMID 37520335, 2022). "The BsAb YG-003D3 was designed to restore the function of depleted T cells for cancer treatment by blocking PD-1/LAG-3 immune checkpoint on immune cells, especially those depleted T cells." (PMID 36518768, 2022). "In this respect, in more severe types of cancer, a phase 1 multicenter study performed the characterization of the lymphocyte-activation gene 3 (LAG-3) inhibitor, ieramilimab." (PMID 35625975, 2022). "The phenomenon of T-cell exhaustion is thought to result from persistent signaling during chronic viral illness and cancers, which seems to be partly driven by LAG3 upregulation." (PMID 35400088, 2022). "As indicated, ICIs against PD-1, PD-L1, CTLA-4, and Lag3 have becoming the promising strategy for the treatments of a variety of malignancies." (PMID 36267966, 2022). "The expression of LAG-3, as well as other molecules involved in immune processes in cancer, is relevant and under investigation all the time." (PMID 36359346, 2022). "In testicular cancer, the overexpression of T cell markers (including LAG-3 and IFNγ) with expressed cancer/testis antigens (e.g., PRAME) in seminomas was found." (PMID 36077354, 2022). "Given its important biological roles, LAG-3 has been regarded as a promising target for cancer immunotherapy." (PMID 35958563, 2022). "This study, using a conditional knock-in mouse model, suggested that LAG-3 acts as a mechanism of primary resistance with advanced cancer receiving checkpoint blockade therapy." (PMID 36009853, 2022). "In the clinical treatment of tumors, immune checkpoints (for instance, CTLA-4, TIM-3, LAG-3, and most importantly, PD-1/PD-L1) have been demonstrated to be effective targets in cancer immunotherapy due to the ability thereof to regulate immune responses." (PMID 35585975, 2022). "The LAG-3 molecule has recently emerged as a promising cancer immunotherapy target and a highly important next-generation immune checkpoint molecule." (PMID 35954196, 2022). "Since its discovery in 1990, LAG3 has gained widespread interest and been regarded as a promising target for cancer immunotherapy." (PMID 35958563, 2022). "LAG-3-targeting cancer immunotherapies have demonstrated good safety profiles, tolerability and adequate pharmacokinetics and pharmacodynamics, with promising antitumor efficacy." (PMID 35755891, 2022). "Other immunoreceptors extensively studied in cancer are LAG-3, TIGIT, T-cell immunoglobulin and mucin containing protein-3 (TIM3) and B and T lymphocyte attenuator (BTLA)." (PMID 35211124, 2022). "We also found differences in cancer-associated fibroblast and macrophage M2 infiltration and the expression of PD-L1, CTLA4, LAG3, and HLA were also observed between the two risk groups (P < 0.05)." (PMID 35144613, 2022). "Emerging immunotherapy, including anti-CTLA4, anti-LAG3, anti-PD-1, and anti-PD-L1 antibodies, has been proven to be efficacious and increased the survival rate of patients with several advanced cancers, including metastatic osteosarcoma patients." (PMID 36276293, 2022). "In this paper, we will review the current state of knowledge on the structure, function and expression of LAG-3 in various types of cancer, as well as its correlation with overall prognosis, involvement in cell-based therapies and experimental medicine." (PMID 36077354, 2022). "As a promising target for cancer immunotherapy, LAG3 has been hotly pursued by academia and pharmaceutical companies." (PMID 35958563, 2022). "The associations of P4HA1 expression with LAG3, ICOS, CTLA4, CD48, TNFSF14, and CD27 expression were inconsistent among cancer types." (PMID 35812752, 2022). "The efficacy of LAG-3-targeting is under investigation in phase I and II clinical trials in a wide variety of cancers." (PMID 35641998, 2022).
cancer (continued). "Among these factors, program death-1 (PD-1), T-cell immunoglobulin and mucin domain-containing molecule 3 (Tim-3), and lymphocyte activation gene-3 (LAG-3) have been reported to be associated with clinical outcomes and prognosis of many cancers." (PMID 36529769, 2022). "On the other hand, the medium-expression group included TNFRSF18, TNFRSF4, CD27, and LAG3 and their expression levels varied significantly among the different cancer samples." (PMID 36157232, 2022). "The combined targeting of the LAG-3 and PD-1 pathways on anti-cancer efficacy raises the possibility that these two ICPs are co-expressed on anergic T cells and work together to facilitate cancer immune evasion." (PMID 36016257, 2022). "Checkpoint blockade therapies (e.g., anti–PD-1, anti–CTLA-4, and anti–LAG-3 therapy, among others) have been developed for multiple cancers." (PMID 36612082, 2022). "This is significant, because simultaneous co-expression of LAG-3 with other immune checkpoint molecules is a distinguishing feature of highly dysfunctional T cells in cancer patients." (PMID 35755891, 2022). "Increased frequencies of LAG3+ Tregs were found in the PBMCs of cancer patients, which expand in the TME to secrete IL-10 and transforming growth factor beta 1 (TGF-β1)." (PMID 35345849, 2022). "Our findings brought to light that PTX3 had a close and positive association with most ICIs (CD274, CTLA4, HAVCR2, LAG3, PDCD1, PDCD1LG2, TIGIT, and SIGLEC15) in TCGA cancers, except TGCT." (PMID 36139597, 2022). "Specifically, it is worth noting that SAAL1 was positively correlated with PD-L1, CTLA-4, and LAG-3 in most cancer types." (PMID 35963646, 2022). "LAG3 is the third cancer immunotherapy to be targeted in the clinic, consequently garnering considerable interest." (PMID 36246624, 2022). "In the present study, it was found that KIF15 was closely related to the expression of LAG3 in 16 out of 33 cancer types." (PMID 35359374, 2022). "Lymphocyte activation gene-3(LAG3) is the third inhibitory receptor exploited in human anti-cancer immunotherapy, behind PD-1 and CTLA-4." (PMID 36528587, 2022). "In this context, LAG-3-targeted therapies have emerged as a cancer immunotherapy alone and in combination with anti-PD-1 treatments." (PMID 35954196, 2022). "In pan-cancer significant association of CD70 and LAG3 expression with poor survival was observed (p < 0.05)." (PMID 35690832, 2022). "Blockade of the FGL1/LAG3 pathway has been exploited by many a researcher as an immunotherapeutic route for cancers." (PMID 34975333, 2022). "Lymphocyte-activation gene 3 (LAG-3) is a critical immune checkpoint marker with implications for a variety of diseases, including cancer." (PMID 36551617, 2022). "Antibodies aimed at blocking the LAG-3/MHC-II interaction are being tested in five active cancer immunotherapy clinical trials (NCT03365791, NCT03499899, NCT02460224, NCT02061761, NCT02658981) and 15 more are currently recruiting at the time of publication." (PMID 35265944, 2022). "Previous studies have shown that the TME interaction with LAG-3 on TILs can modulate an anti-cancer immunoreaction." (PMID 34454491, 2021). "Currently, the most recognized biomarkers (PD-1, PD-L1, CTLA-4, TIM-3, and LAG3) still cannot accurately guide the use of ICIs, resulting in limited clinical benefit for cancer patients." (PMID 34497605, 2021). "Based on these findings, simultaneous blockade of LAG-3 and PD-1 has been employed for cancer therapy." (PMID 34359588, 2021). "MGD013 is a BsAb therapy that simultaneously targets both LAG-3 and PD-1 to suppress immune checkpoint inhibition, promote T cell activation, and improve anti-cancer immunity." (PMID 34454491, 2021). "Intriguingly, a similar correlation pattern between immune modulators and LAG3 was observed in 30 types of cancer, and most immunoinhibitors and immunostimulators positively correlated with LAG3, although a minority of each negatively correlated with LAG3." (PMID 34267742, 2021).